TMBIM1 (transmembrane BAX inhibitor motif containing 1)
Description:
Negatively regulates aortic matrix metalloproteinase-9 (MMP9) production and may play a protective role in vascular remodeling.
Synonyms: LFG3; RECS1; PP1201; MST100; MSTP100
Tractability: Antibody: UniProt places it where antibodies can reach, with high confidence; its Gene Ontology location is reachable by antibodies, with high confidence; UniProt predicts a signal peptide or a membrane-spanning region. PROTAC: its protein half-life has been measured.
Gene: Protein-coding gene on chromosome 2 (218,274,194 to 218,292,586, reverse strand). Ensembl gene ENSG00000135926.
Subcellular location: Membrane; Lysosome membrane; Endosome membrane
Subcellular location (Human Protein Atlas): Vesicles
Pathways (Reactome):
Immune System: Neutrophil degranulation
Gene Ontology:
Molecular function: death receptor binding; protein binding; calcium channel activity
Biological process: negative regulation of extrinsic apoptotic signaling pathway via death domain receptors; negative regulation of Fas signaling pathway; negative regulation of protein localization to plasma membrane; negative regulation of catalytic activity; negative regulation of neuron apoptotic process; positive regulation of blood vessel remodeling; calcium ion transmembrane transport
Cellular component: endosome membrane; extracellular exosome; Golgi apparatus; Golgi membrane; lysosomal membrane; endoplasmic reticulum membrane; plasma membrane; specific granule membrane; membrane
Genetic constraint (gnomAD): Loss-of-function variants: 31 observed, 37.55 expected, observed/expected ratio (o/e) 0.83, 90% interval 0.62 to 1.11. The upper end of that interval is the gene's LOEUF score, 1.11, which puts it in group 4 of 6, group 1 being the genes least tolerant of losing a copy. Missense variants: 306 observed, 324.22 expected, observed/expected ratio (o/e) 0.94, 90% interval 0.86 to 1.04. Synonymous variants: 136 observed, 122.17 expected, observed/expected ratio (o/e) 1.11, 90% interval 0.97 to 1.28.
Homologues: Orthologues: chimpanzee TMBIM1 (99% identical), macaque TMBIM1 (99% identical), rabbit TMBIM1 (93% identical), dog TMBIM1 (91% identical), guinea pig TMBIM1 (90% identical), mouse Tmbim1 (89% identical), rat Tmbim1 (74% identical), tropical clawed frog tmbim1 (68% identical), zebrafish tmbim1a (54% identical), zebrafish tmbim1b (35% identical), Drosophila melanogaster Nmda1 (33% identical), Drosophila melanogaster Lfg (30% identical), and 5 more. Paralogues in human: FAIM2 (49% identical), GRINA (40% identical), TMBIM4 (23% identical), GHITM (15% identical), TMBIM6 (13% identical).
Diseases named in the same sentence as TMBIM1 in open-access papers:
TMBIM1 is named in the same sentence as 25 diseases in open-access papers, as found by Europe PMC text mining. Sharing a sentence is not in itself a finding about the gene and the disease. The quoted sentences say what the papers report.
colorectal cancer (3 papers, 2016 to 2026). A primary or metastatic malignant neoplasm that affects the colon or rectum. "Mounting evidence from large-scale association studies has identified transmembrane BAX inhibitor motif-containing 1 (TMBIM1) as a promising candidate gene in colorectal cancer (CRC) pathogenesis." (PMID 41596730, 2026). "TMBIM1 is highly associated with colorectal cancer risk in the Chinese population and its expression is significantly higher in colorectal cancer tissues." (PMID 41197720, 2025). "Previous studies have found a significant correlation between high TMBIM1 expression and the characteristics of serrated polyposis syndrome, which increases the risk of colorectal cancer." (PMID 41197720, 2025).
Insulin resistance (3 papers, 2021 to 2023). Increased resistance towards insulin, that is, diminished effectiveness of insulin in reducing blood glucose levels. "Prior studies have proved that TMBIM1 promoted lysosomal degradation of TLR4 and inhibited high-fat diet-induced insulin resistance, hepatic steatosis, and inflammation." (PMID 37156795, 2023). "TMBIM1 has been shown to be protective against non-alcoholic fatty liver disease (NAFLD), progression to non-alcoholic steatohepatitis, and insulin resistance in mice and macaques." (PMID 34099068, 2021).
colorectal adenocarcinoma (2 papers, 2016 to 2019). The most common type of colorectal carcinoma. "The authors reported eQTL evidence showing that rs992157 was associated with expression of nearby genes PNKD and TMBIM1 in lymphoblastoid cells, but not colorectal adenocarcinoma cells." (PMID 30820706, 2019).
hepatocellular carcinoma (2 papers, 2021 to 2025). A malignant tumor that arises from hepatocytes. "In a Tmbim1-overexpressed rat model, the occurrence of hepatocellular carcinoma (HCC) was highly inhibited and overall survival was prolonged." (PMID 41197720, 2025).
inflammatory bowel disease (2 papers, 2016 to 2024). A spectrum of small and large bowel inflammatory diseases of unknown etiology. "Thus, PNKD and TMBIM1 may indirectly influence inflammation regulation, a key process in inflammatory bowel disease and CRC development, suggesting their potential impact on CRC via inflammation pathways." (PMID 38631091, 2024).
cardiomyopathy (1 paper, 2021). A disease of the heart muscle or myocardium proper. "Another study on cardiomyopathy revealed that TMBIM1 deficiency exacerbated the inflammation and oxidative stress induced by high fat diet by reducing Nrf2 and Ho-1 while increasing Keap-1 expression in mice." (PMID 34924003, 2021).
colon cancer (1 paper, 2026). "Our clinical analysis confirmed this association, demonstrating significantly reduced TMBIM1 expression in human colon cancer tissues." (PMID 41596730, 2026).
liver cancer (1 paper, 2025). An epithelial or non-epithelial malignant neoplasm that arises from the liver. "To further explore the relationship between TMBIM1 and liver cancer occurrence, we established an N-nitrosodiethylamine (DEN)-induced rat liver cancer model with a period of 0 to 12 weeks representing the period of HCC occurrence." (PMID 41197720, 2025). "Immunohistochemical analysis employing liver tissue microarrays demonstrated a positive expression rate of TMBIM1 was approximately 70% in the peritumoral tissues, whereas the rate in liver cancer tissues was only approximately 20%." (PMID 41197720, 2025). "Through analysis of human tissue specimens and rat liver cancer models, it was confirmed that the expression of TMBIM1 gradually decreased as HCC occurred and that TMBIM1 is associated with the overall survival of patients with HCC." (PMID 41197720, 2025). "We discovered that TMBIM1 exerts inhibitory effects on CS, revealing the molecular mechanism by which TMBIM1 suppresses liver cancer progression." (PMID 41197720, 2025). "We found that TMBIM1 was expressed at higher levels in the adjacent tissues than in the liver cancer tissues." (PMID 41197720, 2025). "Subsequently, we selected four patients to perform Western blot for the TMBIM1 protein in both adjacent and liver cancer tissues, confirming that the protein expression of TMBIM1 was higher in adjacent tissues." (PMID 41197720, 2025). "In our study, TMBIM1 was highly expressed in the adjacent tissues of patients with liver cancer and its expression of TMBIM1 gradually decreased during hepatocarcinogenesis in a rat primary liver cancer model." (PMID 41197720, 2025). "In Tmbim1-overexpressed liver cancer rat models, β-galactosidase staining of frozen sections and immunohistochemical staining of paraffin-embedded sections of liver from rat at 12 W showed fewer senescent cells." (PMID 41197720, 2025). "Additionally, it prolonged the survival period of rats, which is consistent with the finding that TMBIM1 can improve the overall survival of patients with liver cancer." (PMID 41197720, 2025). "Furthermore, long-term follow-up of 70 liver cancer patients showed that the overall survival of 29 patients with high TMBIM1 expression in adjacent tissues was greater than that of 41 patients with low TMBIM1 expression." (PMID 41197720, 2025). "In summary, we have identified TMBIM1 as a significant negative regulator of liver cancer in rats." (PMID 41197720, 2025). "To investigate the expression of TMBIM1 during liver cancer occurrence, we analyzed adjacent nontumor and liver cancer tissues from 70 patients." (PMID 41197720, 2025). "Additionally, overexpressed of TMBIM1 inhibited the formation of tumor nodules and reduced tumor size during DEN-induced liver cancer progression in rats." (PMID 41197720, 2025). "Our study showed that TMBIM1 regulates lysosomal pathways to promote the degradation of TGF-β type I receptors, suppress CS and inhibit HCC, thus providing a novel therapeutic strategy for preventing liver cancer and may shed light on other senescence-related diseases." (PMID 41197720, 2025). "In summary, we found a negative correlation between TMBIM1 and senescence and during HCC occurrence, senescent cells promoted liver cancer progression by inducing the activation of HPCs." (PMID 41197720, 2025).
metabolic syndrome (1 paper, 2021). A cluster of metabolic risk factors for CARDIOVASCULAR DISEASES and TYPE 2 DIABETES MELLITUS. "Higher MT-CN was, in turn, associated with less severe metabolic syndrome, suggesting that TMBIM1 is actually a risk gene, not a protective one." (PMID 34099068, 2021).
non-alcoholic fatty liver disease (1 paper, 2021). "We also report one gene with a rare-variant association with MT-CN, TMBIM1, that has a known link to non-alcoholic fatty liver disease." (PMID 34099068, 2021).
Obesity (1 paper, 2024). Accumulation of substantial excess body fat. "Genetic deletion of the transmembrane BAX inhibitor motif containing 1 (TMBIM1), an inhibitor of adipogenesis, induces visceral adipocyte hyperplasia and improves obesity-related metabolic diseases in HFD-fed mice." (PMID 38256005, 2024).
pancreatic cancer (1 paper, 2025). "Kaplan-Meier survival analyses revealed that elevated TMBIM1 expression was significantly associated with shorter OS among pancreatic cancer patients." (PMID 40083936, 2025). "By knocking down TMBIM1 in a pancreatic cancer model, we observed a significant reduction in MDSC infiltration, which was correlated with improved antitumor immune responses." (PMID 40083936, 2025). "Our study highlights the importance of TMBIM1 in shaping the immune landscape of pancreatic cancer, demonstrating that its inhibition promotes CD8+ T-cell infiltration while reducing MDSC accumulation, thereby enhancing the effectiveness of PD-1 blockade." (PMID 40083936, 2025). "Receiver operating characteristic (ROC) curve analysis revealed that TMBIM1 was highly effective in distinguishing pancreatic cancer tissues from normal tissues, and its expression level was positively correlated with both tumor stage and grade." (PMID 40083936, 2025). "The clinical relevance of TMBIM1 in pancreatic cancer is underscored by our survival analysis of both the TCGA and FUSCC cohorts, where high TMBIM1 expression was significantly associated with poor OS and PFS." (PMID 40083936, 2025). "Taken together, these findings suggest that TMBIM1 promotes pancreatic cancer cell proliferation and migration through mechanisms involving CCL2." (PMID 40083936, 2025). "Collectively, these findings suggest that TMBIM1 functions as a protumorigenic protein in pancreatic cancer." (PMID 40083936, 2025). "To assess the role of TMBIM1 in immune evasion and its effect on the response to immunotherapy, we created a mouse model of in situ pancreatic tumors using Pan02 cells transfected with either control shRNA or shTMBIM1." (PMID 40083936, 2025). "Importantly, this enhancement was further pronounced when TMBIM1 knockdown was coupled with PD-1 blockade, underscoring the role of TMBIM1 in constraining T-cell-mediated immune responses in pancreatic cancer." (PMID 40083936, 2025). "To investigate whether CCL2 acts downstream of TMBIM1 and promotes pancreatic cancer cell proliferation and migration, we utilized the Capan-1 and PANC-1 cell lines." (PMID 40083936, 2025). "Thus, targeting TMBIM1 could serve as a potential therapeutic approach to counteract pancreatic cancer resistance to ICBs." (PMID 40083936, 2025). "After successfully knocking down the TMBIM1 levels in the PANC-1 and Capan-1, we observed significantly suppressed pancreatic cancer cell growth and proliferation, as demonstrated by CCK8 assays." (PMID 40083936, 2025). "We further validated the differential expression of TMBIM1 via the Gene Expression Omnibus (GEO) datasets GSE32688 and GSE15471, confirming its elevated expression in pancreatic cancer tissues compared with normal tissues from healthy controls." (PMID 40083936, 2025).
paroxysmal non-kinesigenic dyskinesia (1 paper, 2016). "The combined analysis identified a new risk association for CRC at 2q35 marked by rs992157 (P = 3.15 × 10−8, odds ratio = 1.10, 95% confidence interval = 1.06–1.13), which is intronic to PNKD (paroxysmal non-kinesigenic dyskinesia) and TMBIM1 (transmembrane BAX inhibitor motif containing 1)." (PMID 27005424, 2016). "rs992157 is located at 2q35, and is intronic to two genes: paroxysmal non-kinesigenic dyskinesia (PNKD) on the forward strand and transmembrane BAX inhibitor motif containing 1 (TMBIM1) on the reverse strand." (PMID 27005424, 2016).
cancer (6 papers, 2014 to 2025). A tumor composed of atypical neoplastic, often pleomorphic cells that invade other tissues. "Using the ONCOMINETM database, we compared the expression patterns of the TMBIM family genes (TMBIM1-6) in normal and cancer tissues." (PMID 37057283, 2023). "Further investigation on the role of TMBIM1 in cancer would be warranted." (PMID 34924003, 2021). "Besides, the relationship between TMBIM1 and antioxidants in cancer is unknown." (PMID 34924003, 2021). "In addition, the relationship between TMBIM1 and antioxidants in cancer is unknown." (PMID 34924003, 2021). "Members of the TMBIM family such as TMBIM1, TMBIM2, TMBIM4, and TMBIM5 are found to be expressed highly in various cancers and also play an important role in cell adhesion and migration." (PMID 31336725, 2019). "Interestingly, TMBIM1, TMBIM2, TMBIM4, and TMBIM5 were found to decrease in many types of cancer, but TMBIM3 and TMBIM6 were significantly increased in this analysis." (PMID 37057283, 2023). "Of note, there is no comprehensive study about the effects of TMBIM1 on cancer formation and growth." (PMID 34924003, 2021).
tumor (6 papers, 2021 to 2026). "We therefore define a context-dependent tumor-suppressive mechanism for TMBIM1, wherein its loss in MSI-H cells promotes tumorigenesis via E-cadherin suppression and the consequent loss of epithelial integrity." (PMID 41596730, 2026). "Mouse models demonstrate that TMBIM1 knockdown combined with anti-PD-1 therapy achieves superior anti-tumor effects compared with anti-PD-1 monotherapy." (PMID 41346602, 2025). "Functional studies demonstrate that TMBIM1 knockdown combined with anti-PD-1 therapy achieves superior anti-tumor effects compared with monotherapy." (PMID 41346602, 2025). "Immunohistochemical analysis of these tumors revealed reduced expression of Ki67, a marker of cell proliferation, in the TMBIM1-knockdown group, further underscoring the role of TMBIM1 in promoting tumor growth." (PMID 40083936, 2025). "Elevated TMBIM1 expression induced high infiltration of MDSCs and fostered an immunosuppressive tumor microenvironment." (PMID 40083936, 2025). "On the basis of these results, we established that TMBIM1 modulates tumor CCL2 and PD-L1 expression through the regulation of YBX1." (PMID 40083936, 2025). "The tumor growth data demonstrated that the combination of TMBIM1 knockdown and anti-PD-1 treatment led to significantly smaller tumors than either treatment alone or the control." (PMID 40083936, 2025). "Tumor cells were stratified into high and low TMBIM1 expression groups, resulting in the identification of 2,227 upregulated and 1,345 downregulated genes through differential gene expression analysis." (PMID 40083936, 2025). "The results revealed that tumors from the TMBIM1-OE group had a significantly greater tumor burden than those from the control group did." (PMID 40083936, 2025). "To investigate the role of TMBIM1 in tumor progression in vivo, we overexpressed TMBIM1 in the mouse PDAC cell line Pan02." (PMID 40083936, 2025). "Strikingly, TMBIM1 overexpression unexpectedly enhanced tumor invasiveness and promoted tumor growth." (PMID 41197720, 2025). "We observed that cellular senescence reversed the anti-tumor effects of TMBIM1." (PMID 41197720, 2025). "Functional assays demonstrated that TMBIM1 promotes tumor cell proliferation and migration." (PMID 40083936, 2025). "Moreover, Rab9a downregulation reversed the tumor-suppressive effect of Tmbim1, indicating that Rab9a is essential for TMBIM1-mediated suppression of tumor progression through the proposed mechanism." (PMID 41197720, 2025). "Notably, combining TMBIM1 knockdown with anti-PD-1 therapy elicited a robust immune response against PDAC tumor cells." (PMID 40083936, 2025). "Notably, NAC and GSH promoted tumor formation and growth by reducing ROS and induction of TMBIM1 in DEN-induced murine hepatocarcinogenesis." (PMID 35628208, 2022). "Analysis of the isolated and homogenized tumor samples revealed that the intratumoral levels of CCL2 and PD-L1 were notably elevated in the TMBIM1-OE tumors." (PMID 40083936, 2025). "In this model, TMBIM1 inhibited the occurrence of HCC, as evidenced by better liver condition, fewer tumor nodules and smaller sizes in the AAV8-Tmbim1 group at 10, 12 and 14 weeks." (PMID 41197720, 2025). "Transmembrane protein TMBIM1 is markedly upregulated in PDAC tissues and cells, promoting tumor proliferation, migration, and growth while inducing substantial MDSC infiltration." (PMID 41346602, 2025). "Transmembrane BAX inhibitor motif-containing protein 1 (TMBIM1) is highly expressed in PDAC tissues and cell lines, promoting tumor cell proliferation, growth, and migration while inducing substantial MDSC infiltration." (PMID 41346602, 2025). "We have identified that the expression of TMBIM1 is higher in the adjacent nontumor tissues of HCC patients than in the tumor tissues and gradually decreases in DEN-induced rat models." (PMID 41197720, 2025).
tumor (continued). "These senescent TMBIM1-overexpressing cells (or nonsenescent controls) were then co-inoculated subcutaneously with tumor cells into nude mice." (PMID 41197720, 2025). "In the realm of research concerning the role of TMBIM1 in HCC, one study has showed that TMBIM expression was induced by exogenous antioxidants N-acetylcysteine and glutathione to promote HCC development and aggravate tumor aggression." (PMID 41197720, 2025). "Based on our findings, we hypothesize that TMBIM1 may facilitate tumor progression and malignancy by suppressing cellular senescence in tumor cells, a possibility that has not been further explored in the present study." (PMID 41197720, 2025).
infection (1 paper, 2025). The state of being infected such as from the introduction of a foreign agent such as serum, vaccine, antigenic substance or organism. "After 48 h of infection of lentivirus to overexpress Tmbim1 in the hepatocytes (LV-Tmbim1 group), cells displaying viral fluorescence were observed under a microscope with nearly 100% of the cells exhibiting the expected phenotype." (PMID 41197720, 2025).
TMBIM1 also shares sentences with these, for which no sentence is quoted: Hepatic steatosis (2 papers); cardiac hypertrophy (1); diabetes (1); epilepsy (1); glioblastoma (1); metabolic disease (1); non-alcoholic steatohepatitis (1); pancreatic adenocarcinoma (1); systemic sclerosis (1).